NDRG1 (N-myc downstream regulated 1)
Diseases named in the same sentence as NDRG1 in open-access papers (continued):
Sharing a sentence is not in itself a finding about the gene and the disease.
renal cell carcinoma (3 papers, 2013 to 2023). "In renal cell carcinoma, the suppression of NDRG1 gene expression in vitro significantly increased renal cell proliferation and invasion." (PMID 37858101, 2023). "Therefore, Tgfa and Ndrg1 displayed a similar HIF2α specificity in these tissues as in renal cell carcinoma WT8 cells but not induced in the Vhl-deficient kidney tissue (see discussion)." (PMID 33321829, 2020). "Therefore, it is also possible that USF2 also participates in the HIF2α-dependent expression of PHD3, OCT-4, NDRG1, TGFA, GLUT1, CCND1 and SLC7A5 in renal cell carcinoma." (PMID 33321829, 2020). "In this line Tgfa and Ndrg1 expression is induced by HIF2α in renal cell carcinoma WT8 cells while is not induced in Vhl−/− kidneys." (PMID 33321829, 2020). "In contrast, knockdown of FOXD3 decreased the in vitro growth and invasion capabilities of renal cell carcinoma 786-O cells, without changes in the NDRG1 expression." (PMID 24269992, 2013).
bladder tumour (2 papers, 2019 to 2025). "The results of the real-time PCR and western blot analyses revealed that the NDRG1 mRNA (p = 0.040) and protein (p = 0.002) expression levels were significantly higher in bladder tumour tissues than in paired tumour-free tissues." (PMID 30914736, 2019). "We found that seven of these genes, IGFBP3, VEGF, CCNG2, NDRG1, PFKFB3, ADM and SLC2A1, were also upregulated in MIBC and/or NMIBC in our study, suggesting parallel hypoxia-induced expression changes with primary bladder tumour tissue." (PMID 40867253, 2025).
brain tumors (2 papers, 2023 to 2024). "We present a study investigating the expression of NDRG1 in a clinical cohort of matched breast and metastatic brain tumours, and demonstrate the importance of NDRG1 subcellular localisation in prognostication." (PMID 40530439, 2024). "For example, similar expression levels of NDRG1, LDHA, MHCII molecules, interferon genes, GPM6A, C9, and SRGAP2 were discovered in different myeloid subpopulations, indicating the similar functional states in different brain tumors." (PMID 38094301, 2023).
Charcot-Marie-Tooth disease (2 papers, 2014 to 2016). An inherited degenerative disorder involving the peripheral nerves. "N-myc downstream-regulated gene 1 (NDRG1) is induced by cellular stress such as hypoxia and DNA damage, and in humans, germ line mutations cause Charcot-Marie-Tooth disease." (PMID 24498060, 2014). "NDRG1 is the most widely studied protein, namely for its role in peripheral myelination since a mutation in this gene leads to a severe autosomal recessive demyelinating neuropathy, NDRG1-linked Charcot-Marie-Tooth Disease (CMT4D)." (PMID 27902705, 2016). "NDRG1 missense mutations cause hereditary motor and sensory neuropathy-Lom (HMSNL), an autosomal recessive form of Charcot-Marie-Tooth disease (CMT) also called CMT4D." (PMID 24498060, 2014).
colitis (2 papers, 2023 to 2024). Inflammation of the colon. "Consistent with previous work, in the DSS mouse model, the expression levels of Cd44, S100a8, S100a9 and Timp1 were greater in the mice with colitis; while the expression level of Ndrg1 was lower in the mice with colitis." (PMID 38778086, 2024). "Accordingly, the potential connection between miR-199a and Ndrg1 pathway may be related to the development of colitis." (PMID 37370489, 2023). "Given the altered lipid profile observed in mice with colitis, it is worth investigating whether miR-199a/Ndrg1 pathway can modulate lipogenesis and lipolysis during colitis in future studies." (PMID 37370489, 2023). "It was not surprising that the expression levels of CIDEC, NUMA1 and RAG1 in human subjects; Ndrg1 and Pea15a in mice with TNBS-induced colitis; and Cidec, Pea15a and Xbp1 in mice with DSS-induced colitis were not significantly different given the small sample sizes." (PMID 38778086, 2024).
cutaneous melanoma (2 papers, 2022 to 2025). A primary melanoma arising from atypical melanocytes in the skin. "However, unlike previous findings, our qPCR results revealed high expression levels of NDRG1 in skin melanoma tissues." (PMID 41409301, 2025). "The three CCP-related gene signatures–HSD11B1, NDRG1 and CDCA3–may each independently predict the clinical outcomes of cutaneous melanoma patients, according to our prognostic study (both in OS and DSS)." (PMID 36713580, 2022).
demyelinating peripheral neuropathy (2 papers, 2013 to 2018). "The demyelinating peripheral neuropathy Charcot Marie Tooth disease type 4D (CMT4D) is caused by homozygous null mutations in the NDRG1 gene." (PMID 29898756, 2018). "Of these,Ndrg1 was considered as an especially good candidate since mutations in the human orthologue have been shown to be the cause of a demyelinating peripheral neuropathy, Charcot-Marie-Tooth disease type 4D10." (PMID 24715951, 2013).
endometrial cancer (2 papers, 2021). Primary or metastatic malignant neoplasm involving the endometrium (mucous membrane that lines the endometrial cavity). "MiR-449a suppressed the growth and metastasis of endometrial cancer by directly targeting the NDRG1 gene and miR-26a promoted invasion/metastasis by inhibiting PTEN and inhibited cell proliferation by repressing EZH2 in HCC." (PMID 33681289, 2021). "Paradoxically, NDRG1 is also a putative tumor suppressor since it has been found downregulated in several types of cancers, such as prostate, pancreatic, and endometrial cancers." (PMID 34307149, 2021).
head and neck cancer (2 papers, 2022 to 2025). A primary or metastatic malignant neoplasm affecting the head and neck. "We surveyed and characterized the role of NDRG1 in head and neck cancer (HNC)." (PMID 35563887, 2022). "Among them, 6 genes were highly expressed in head and neck cancers, namely SLC1A5, ETS1, NDRG1, RHEB, HIF1A and CDH2." (PMID 41317550, 2025).
laryngeal carcinoma (2 papers, 2021 to 2022). Carcinoma that arises from the laryngeal epithelium. "For example, the tumor suppressor NDRG1 and NDRG2 present highly methylated and low protein expression status in laryngeal cancer, suggesting that abnormal methylation on the NDRG1/2 promoter region may be an early event in laryngeal cancer initiation." (PMID 35287752, 2022).
malignant glioma (2 papers, 2015). A grade III or grade IV glioma arising from the central nervous system. "Therefore, the present study aimed to investigate whether the expression of NDRG1 was associated with the progression of malignant glioma." (PMID 25777142, 2015).
Obesity (2 papers, 2021 to 2024). Accumulation of substantial excess body fat. "Zonal expression of the HIF target gene, N-myc downstream regulated 1 (Ndrg1) was noted, whereas expression of m6A demethylase Fat mass and obesity associated (Fto) gene was comparable across the liver lobule." (PMID 38227578, 2024). "In this scenario, p38 kinase activity could be a possible positive regulator of NDRG1 phosphorylation at T346 during obesity." (PMID 34956089, 2021).
oral cancer (2 papers, 2018 to 2022). "In favor of a tumor-suppressive function, NDRG1 was found to inhibit cell proliferation, invasion, and tumorigenesis in oral cancer cells." (PMID 35563887, 2022). "Our group has shown for the first time that NDRG1 is also one of the CAPE downstream genes in oral cancer cells." (PMID 29738439, 2018). "Previously, our group has proven that CAPE could repress oral cancer cell growth through upregulation of NDRG1." (PMID 29738439, 2018). "NDRG1 has been widely deemed as a tumor suppressor gene in lots of cancers, including oral cancer." (PMID 29738439, 2018).
serous ovarian cancer (2 papers, 2021 to 2024). "Notably, NDRG1 was amplified in 31% of these 1880 patients, with gene amplification being the predominant alteration in different types of serous ovarian cancer." (PMID 38987777, 2024).
adenoma (1 paper, 2021). A neoplasm arising from the epithelium. "The univariable analyses performed on a well-characterized cohort (the Swedish Watchful Waiting Cohort after TURP or adenoma enucleation), revealed a positive association of increased expression of APOE, YWHAZ, and NDRG1 with poor OS." (PMID 33483585, 2021).
astrocytomas (1 paper, 2004). "In both astrocytomas and hemangioblastomas there was intense staining for both Ndrg1 and HIF-1α in a number of different patients." (PMID 15341671, 2004).
atherosclerosis (1 paper, 2025). A disease characterized by the build-up of fatty material and calcium deposition in the arterial wall resulting in partial or complete occlusion of the arterial lumen. "Although our study demonstrates that PIM1 promotes the phosphorylation of NDRG1, leading to its nuclear translocation and the subsequent progression of EndMT and atherosclerosis, it is important to note that other mechanisms by which NDRG1 promotes atherosclerosis progression still exist." (PMID 39744686, 2025). "Once inside the nucleus, NDRG1, through the RNA-binding function of PTBP1, promotes EndMT, leading to decreased stability of atherosclerotic plaques and accelerated progression of atherosclerosis." (PMID 39744686, 2025). "This indicates that regardless of the mechanism by which NDRG1 promotes the progression of atherosclerosis, Max-40279 could be a potential therapeutic option for atherosclerosis by inhibiting NDRG1." (PMID 39744686, 2025).
autoimmune uveitis (1 paper, 2015). An autoimmune form of uveitis (disease). "For this purpose, we induced experimental autoimmune uveitis by injecting the old Ndrg1-knockout mice with uveitogenic peptides." (PMID 26507712, 2015).
avian influenza (1 paper, 2019). Infection of domestic and wild fowl and other birds with influenza A virus. "Conversely, the IAVs are enveloped viruses with a single-stranded, negative-sense RNA genome, and recent evidence suggests that NDRG1 plays a positive role in avian influenza (highly pathogenic avian influenza [HPAI]) A/H5N1 virus replication by suppressing the canonical NF-κB signaling pathway." (PMID 31189711, 2019).
brain cancer (1 paper, 2024). A primary or metastatic malignant neoplasm affecting the brain. "To further validate the research results, we utilized the HPA database to analyze the expression of the NDRG1 gene in various brain cancer cell lines, and the results showed that NDRG1 was upregulated in multiple brain cancer cell lines." (PMID 39668822, 2024).
cervical adenocarcinoma (1 paper, 2019). An adenocarcinoma arising from the cervical epithelium. "In cervical adenocarcinoma, high NDRG1 expression was directly associated with shorter progression-free survival and overall survival." (PMID 30914736, 2019).
Cirrhosis (1 paper, 2013). A chronic disorder of the liver in which liver tissue becomes scarred and is partially replaced by regenerative nodules and fibrotic tissue resulting in loss of liver function. "NDRG1 expression is not affected by pathological conditions of the liver, for example, hepatitis and cirrhosis, or by different types of hepatitis virus infection." (PMID 24260043, 2013).
cortical dysplasia (1 paper, 2017). "And FSCN1, CRMP1, NDRG1, DPYSL5, MAP4, and FABP3 were selected for validation and identified to be increased in childhood cortical dysplasia patients, while PRDX6 and PSAP were identified decreased." (PMID 28222113, 2017).
COVID-19 (1 paper, 2024). A disease caused by infection with severe acute respiratory syndrome coronavirus 2. "In blood, there was upregulation of inflammatory (AREG) and vascular damage (NDRG1) genes in COVID-19 in monocytes but no upregulation of IFNG or IFN-γ response genes." (PMID 39567718, 2024).
dementia (1 paper, 2025). Loss of intellectual abilities interfering with an individual's social and occupational functions. "Similarly, proteins such as MMP8, IL32, NDRG1, SMOC2, or ESM1, which have been previously reported to contribute to AD pathology, showed to be significantly increased in both MCI A + T + and AD dementia, but not in MCI A-T-, suggesting a specific AD-related signature in pEVs proteome." (PMID 41282153, 2025).
esophageal tumor (1 paper, 2019). "Previous research has shown that TLE2 was significantly suppressed and the level of β-catenin protein was increased in esophageal tumor cells, both of which were modulated by NDRG1 overexpression." (PMID 31766561, 2019).
eye inflammation (1 paper, 2015). "Despite a low frequency of overall disease induction, Ndrg1-knockout mice showed more severe eye inflammation than the wild-type mice." (PMID 26507712, 2015).
glioblastoma of brain (1 paper, 2004). "In some cases (especially glioblastoma of brain) the expression of Ndrg1 coincided with HIF-1 protein, indicating that induction of HIF-1α by hypoxia probably resulted in Ndrg1 accumulation in these cancers." (PMID 15341671, 2004).
Head-Neck Squamous Cell Carcinoma (1 paper, 2022). "Differential expression of NDRG1 between normal and tumor tissues was examined using The Cancer Genome Atlas Head-Neck Squamous Cell Carcinoma (TCGA-HNSC) dataset." (PMID 35563887, 2022).
Hyperglycemia (1 paper, 2024). An increased concentration of glucose in the blood. "First, we combined scRNA-seq data from humans with high-throughput sequencing data from a mouse model of hyperglycemia and two renal fibrosis models from rats to ensure the stability of NDRG1 in different species." (PMID 39092227, 2024).
in situ carcinoma (1 paper, 2024). A malignant epithelial neoplasm which is confined to the epithelial layer without evidence of further tissue invasion. "Moreover, spatial proteomics analysis revealed that NDRG1 was most abundant in the tumor core, peripheral tumor, and in situ carcinoma compared to intra-tumoral fibrosis and healthy tissue." (PMID 39736699, 2024).
Infertility (1 paper, 2022). "Therefore, to investigate the association between endometrial receptivity and NDRG1, we evaluated NDRG1 expression in the proliferative and secretory phase of the normal endometrium and in the secretory phase of infertility." (PMID 36293154, 2022). "In this study, miR-182 was downregulated in the mid-secretory phase of the endometrium, and its target gene, NDRG1, was upregulated when compared to expression observed during the proliferative and secretory phases of infertility." (PMID 36293154, 2022). "However, NDRG1 protein abundance was lower in infertile versus normal endometrium tissues, although the difference was not significant." (PMID 36293154, 2022).
invasive carcinoma (1 paper, 2024). A carcinoma that is not confined to the epithelium, and has spread to the surrounding stroma. "NDRG1 high cases were enriched for invasive carcinoma‐no special type (IC‐NST), mixed types of carcinomas (excluding mixed ductal–lobular) and metaplastic BC, whereas mixed ductal–lobular invasive carcinomas showed the lowest proportion." (PMID 40530439, 2024).
invasive ductal carcinoma (1 paper, 2024). "NDRG1 over-expression was observed in invasive ductal carcinoma (IDC; p = 0.01)." (PMID 39736699, 2024).
keratoconus (1 paper, 2023). A degenerative, structural disorder of the eye, characterized by a cone-shaped protrusion of the cornea. "A trio-exome NGS study suggests NDRG1 as a candidate gene in the pathogenesis of keratoconus due to its involvement in the organization of the cytoskeleton." (PMID 37895187, 2023). "NDRG1 (OMIM: #605262) is also an important regulator of the VEFG factor that is essential for the maintenance of the balance between anti-angiogenic and angiogenic factors to maintain corneal avascularity and transparency, relevant in the development of keratoconus." (PMID 37895187, 2023).
limb-girdle muscular dystrophy type 2G (1 paper, 2024). "Our findings of new founder mutations in the NDRG1 gene makes CMT4D the second most common autosomal recessive disorder described in this ethnic group after limb-girdle muscular dystrophy type 2G." (PMID 39201732, 2024).
liver diseases (1 paper, 2017). "Of these disease-associated proteins and proteins related to Galectin-3, NDRG1 showed a close relationship to carcinoma and liver diseases, and CD166, S100A11 and Galectin-1 were also related to carcinoma." (PMID 28701735, 2017).
lung squamous cell carcinoma (1 paper, 2022). "NDRG1 was also highly expressed in HCC, lung squamous cell carcinoma, and head and neck squamous carcinoma." (PMID 36686830, 2022).
myeloma (1 paper, 2020). "In conclusion, we have identified that the combination of trametinib and dexamethasone is synergistic in RAS-mutant myeloma cells, particularly in those with elevated NDRG1 expression and is associated with suppression of PDK1 signalling." (PMID 32228485, 2020).
nervous system cancer (1 paper, 2019). A primary or metastatic malignant neoplasm involving the nervous system. "In the context of nervous system cancers, NDRG1, NDRG2, and NDRG4 have been described to be tumor suppressor genes, although some results are not consistent throughout different studies." (PMID 31485792, 2019).
Niemann-Pick type C disease (1 paper, 2019). "Interestingly, a genomewide expression analysis of fibroblasts derived from a patient with Niemann-Pick type C disease showed that NDRG1 mRNA levels were elevated." (PMID 31189711, 2019).
osteoporosis (1 paper, 2022). A condition of reduced bone mass, with decreased cortical thickness and a decrease in the number and size of the trabeculae of cancellous bone (but normal chemical composition), resulting in increased fracture incidence. "Taken as a whole, this study suggests that NDRG1 is an attractive option for the therapeutic intervention of metabolic disorders such as osteoporosis." (PMID 35120575, 2022).
ovarian tumors (1 paper, 2024). "Notably, our BioID analysis also identified NDRG1 as a potential claudin-4-interating protein in ovarian tumor cells, with more than twice the number of peptides identified for this protein compared to control cells." (PMID 38867360, 2024). "Subsequently, the corresponding genes of the total enriched proteins were analyzed in cBioportal (datasets of ovarian tumors) to identify highly mutated elements directly associated with the claudin-4-interacting proteins, revealing BRD4, CCDC130, PTK2, and NDRG1 as the most mutated elements." (PMID 38867360, 2024).
Parkinson disease (1 paper, 2025). A progressive degenerative disorder of the central nervous system characterized by loss of dopamine producing neurons in the substantia nigra and the presence of Lewy bodies in the substantia nigra and locus coeruleus. "In Parkinson’s disease, NDRG1 expression was demonstrated to be high in astrocytes in the cerebral cortex of adult 57BL/6J mice." (PMID 40378957, 2025).
Pleural effusion (1 paper, 2023). The presence of an excessive amount of fluid in the pleural cavity. "We treated SUM159, BT549 (both established from primary tumor), MDA-MB-231, and MDA-MB-436 (both derived from pleural effusion) with TGFβ1 and, 8h later, the NDRG1 gene was knocked down for 48h (8+48 protocol)." (PMID 36594086, 2023). "In the same way, soft-agar colony formation provided similar findings as only knockdown of NDRG1 with TGFβ1 led to a reduced number of colonies in primary-tumor- and pleural-effusion-derived cell lines." (PMID 36594086, 2023). "Hence, we studied whether NDRG1 could have a differential role on EMT upon TGFβ1 stimulation by western blot in primary-tumor- or pleural-effusion-derived cell lines." (PMID 36594086, 2023).
prostate hyperplasia (1 paper, 2021). "The relative expression of N-cadherin, NDRG1, and AR was evaluated in prostate hyperplasia (BPH-1), androgen-dependent PCa (ADPC) (LNCaP), and CRPC (PC3) cell lines." (PMID 34512147, 2021).
pulmonary fibrosis (1 paper, 2023). Chronic progressive interstitial lung disorder characterized by the replacement of the lung tissue by connective tissue, leading to progressive dyspnea, respiratory failure, or right heart failure. "The progression of pulmonary fibrosis can be slowed down by regulating EMT through Bach1, ZEB1, NDRG1, erastin, liproxstatin-1, Cav-1 and other ferroptosis-related genes or proteins." (PMID 36672671, 2023).